TMPRSS2 (transmembrane serine protease 2)
Diseases named in the same sentence as TMPRSS2 in open-access papers (continued):
Sharing a sentence is not in itself a finding about the gene and the disease.
lung carcinoma (continued). "Surprisingly, in AR/TMPRSS2 double-positive H2126 and H1437 lung cancer cells, neither AR inhibition using enzalutamide nor AR stimulation using DHT resulted in a significant change in TMPRSS2 expression, implying that AR cannot regulate TMPRSS2 expression in human lung cancer cells." (PMID 33558541, 2021). "Mechanistically, long-term exposure of lung cancer cells to PM2.5 may promote lung cancer progression through activation of the Aryl hydrocarbon receptor (AhR) and epidermal growth factor receptor (EGFR), which boosts the Serine protease pathway transmembrane 2 (TMPRSS2)-IL8 pathway." (PMID 38299096, 2023). "However, TMPRSS2 should not be targeted in lung cancer patients infected with SARS-CoV-2." (PMID 34168096, 2021). "Syncytium formation was observed in VeroE6/TMPRSS2, Rc, and iMylc-D05-s-ML2 cells by 48 hpi, but not in BHK cells, human lung cancer-derived Calu-3 cells, or porcine kidney-derived PK-15 cells." (PMID 40303027, 2024). "By contrast, in H1299 lung cancer epithelial cells, Hela-ACE2 (overexpressing ACE2), and 293T cells overexpressing ACE2 and deleted for TMPRSS2 (293T-A2ΔT2), we did not observe large differences in entry efficiency for Delta and Omicron." (PMID 35075452, 2022). "Interestingly, we found that TMPRSS2 expression was significantly lower in both HNSCC-COVID19 patients and lung cancer tissues compared to matched non-tumorous counterparts." (PMID 32967703, 2020). "Utilizing multiple models, including human lung cancer cells, human lung organoids and Ad-ACE2-transduced WT mice, we demonstrated that enzalutamide failed to inhibit SARS-CoV-2 infection, which was attributed to the lack of AR-driven modulation of TMPRSS2 expression in lung epithelial cells." (PMID 33558541, 2021).
influenza (58 papers, 2012 to 2026). An acute viral infection of the respiratory tract, occurring in isolated cases, in epidemics, or in pandemics; it is caused by serologically different strains of viruses (influenzaviruses) designated A, B, and C, has a 3-day incubation period, and usually lasts for 3 to 10 days. "Another example would be the SNP, rs2070788, which has been associated with increased TMPRSS2 expression levels, suggesting the contribution of TMPRSS2 to severe influenza A (H1N1) pdm09 and A (H7N9) infections." (PMID 40297833, 2025). "Polymorphisms of the TMPRSS2 gene have been shown to affect susceptibility to and severity of influenza infections." (PMID 40297833, 2025). "A second SNP, rs383510, which lies in a regulatory region, similarly influences TMPRSS2 expression and is associated with susceptibility to these influenza strains." (PMID 40297833, 2025). "Genetic factors such as polymorphisms that moderate the expression of TMPRSS2 have demonstrated predictive value in the susceptibility and severity of influenza infections." (PMID 40297833, 2025). "Increased TMPRSS2 expression has been associated with a higher risk of severe influenza infection and enhanced susceptibility to SARS-CoV-2." (PMID 37208193, 2023). "In contrast, overexpression of certain TMPRSS2 variants in animals results in an increased risk of severe outcomes after infection with A (H1N1) pmd09 influenza." (PMID 35017320, 2022). "During the H1N1 epidemic in 2009, the TMPRSS2 variant that resulted in increased expression was associated with increased human susceptibility to influenza infection." (PMID 35017320, 2022). "Further studies found that polymorphism in the TMPRSS2 protein can affect the severity of influenza in humans." (PMID 34336361, 2021). "For human/SARS-CoV-2 interactome genes ACE2, TMPRSS2 and BSG, there is a convincing evidence of association in Asians with influenza-induced SARS for TMPRSS2-rs2070788, tag-SNP of the eQTL rs383510." (PMID 34436507, 2021). "Considering that influenza virus entry also utilizes TMPRSS2 for the cleavage of viral hemagglutinin (HA) protein, the genetic association of TMPRSS2 variants and influenza infection was previously investigated." (PMID 33133166, 2020). "Such a scenario would be in keeping with the findings that TMPRSS2 expression is required for spread of several influenza A viruses (FLUAV) in mice and that polymorphisms in TMPRSS2 impact severity of influenza in human patients." (PMID 28636671, 2017). "Although experimental evidence for enhanced IAV activation and spread in the human airways because of TMPRSS2 gene polymorphisms is missing, the study highlighted that elevated levels of TMPRSS2 might provide a predisposition for severe influenza outcomes." (PMID 37208193, 2023). "TMPRSS2 thus accomplishes both primary cleavage of Spike and secondary integration with the host-cell membrane, achieving such steps both for coronavirus infections and for various influenza variants." (PMID 37987478, 2023). "Understanding ACE2 and TMPRSS2 protein expression at the transcription level in the human cells could reveal important insights into differential susceptibility to influenza and coronavirus infections and novel targets for therapeutic purposes." (PMID 34445373, 2021). "Furthermore, studies regarding the TMPRSS2 gene polymorphisms that cause TMPRSS2 gene overexpression in humans, showed its association with severe influenza." (PMID 34527703, 2021). "We suggest that using these inhibitors may be therapeutic in conditions in which TMPRSS2 function is pathogenic, such as in several types of coronavirus and influenza infections." (PMID 33969249, 2021). "In the same study, rs2070788 and rs383510 variants were significantly associated with higher risk to severe A(H1N1)2009 and A(H7N9) influenza, with individuals carrying the increased TMPRSS2 expression alleles being at approximately twofold higher risk for severe infection." (PMID 33243086, 2020).
influenza (continued). "Moreover, polymorphisms in TMPRSS2 were shown to impact severity of influenza in humans." (PMID 27028521, 2016). "In the human lung organoids, infection of SARS-CoV-2 delta variants upregulated α−2–3-linked sialic acid, while influenza infection increased the expression of angiotensin-converting enzyme 2 (ACE2) and transmembrane serine protease 2 (TMPRSS2)." (PMID 39883362, 2025). "This field of research is highly significant because it has the potential to significantly enhance outcomes from therapy for influenza and coronavirus infections by tailored inhibition of TMPRSS2." (PMID 40297833, 2025). "Addressing TMPRSS2 is a viable technique for developing antiviral medications for influenza and coronaviruses, emphasizing its role in viral pathogenesis and therapy." (PMID 40297833, 2025). "Respiratory viruses, such as SARS‐CoV‐2 and influenza, exploit host proteases like TMPRSS2 for entry, making TMPRSS2 a prime antiviral target." (PMID 40365759, 2025). "Knockout of the transmembrane serine protease 2 gene (TMPRSS2) increased pig resistance to influenza, represented by delayed viral replication, lower virus titers, and significantly fewer lung lesions in the lower respiratory tract." (PMID 41465565, 2025). "It is crucial for viral membrane fusion and RNA entry into the cell, indicating that there is a differential dependence on TMPRSS2 between different influenza subtypes and allowing for initiating infection." (PMID 40297833, 2025). "The essential role of TMPRSS2 in promoting replication is underscored by evidence showing that its deletion confers resistance to influenza in mice." (PMID 41042757, 2025). "TMPRSS2 is involved in the direct proteolytic activation of many viral glycoproteins and was first identified as a viral cofactor for influenza." (PMID 38932275, 2024). "TMPRSS2 inactivation in mice was shown to increase their resistance to several strains of influenza and to SARS-CoV-2 infection." (PMID 37660915, 2023). "Transmembrane serine protease 2 (TMPRSS2) is a protease mediating the cleavage of viral envelope and spike proteins of various viruses (including influenza and severe acute respiratory syndrome coronavirus 2 [SARS-CoV-2])." (PMID 37660915, 2023). "Various small molecule, peptide and protein inhibitors of TMPRSS2 have been identified which efficiently block influenza and coronavirus infection and replication in vitro and in animal models." (PMID 35163273, 2022). "Influenza and coronaviruses significantly depend on the TMPRSS2 gene for viral entry and spread inside a host, using similar mechanisms." (PMID 35193695, 2022). "The structure of extracellular domain of MSPL and inhibitor complex helps to understand the TTSP functions, including TMPRSS2, and provides the insights of the infection of influenza and SARS-CoV." (PMID 33820827, 2021). "It is demonstrated that genetic variation in TMPRSS2 including two identified SNP in TMPRSS2 (rs383510 and rs2070788) had a strong correlation with the A (H7N9) influenza susceptibility." (PMID 34527703, 2021). "ACE2 receptor downregulation occurred specifically in females in Th2 high asthma, while proteases broadly assisting coronavirus and influenza viral entry, TMPRSS2, and TMPRSS4, were highly upregulated in both sexes." (PMID 34198852, 2021). "Plasminogen inhibitor (PAI)-1 (SERPINE1) has been reported to function as an anti-viral factor capable of inhibiting extracellular maturation of influenza particles, specifically through their action on TMPRSS2." (PMID 34786557, 2020). "For example, a splice switching morpholino oligonucleotide can restrict influenza viral replication by suppressing exon inclusion of the host transmembrane serine protease 2 (TMPRSS2)." (PMID 31921062, 2019). "Previous studies have examined these proteases in the context of influenza infections, specifically TMPRSS2 and HAT." (PMID 22496898, 2012).
influenza (continued). "Our observations also suggest that TMPRSS2 can support influenza virus spread in species integral to the influenza zoonosis, and that mice are suitable models to study the role of TMPRSS2, TMPRSS4 and HAT in viral spread and pathogenesis." (PMID 22558251, 2012). "Although previous studies have demonstrated the importance of TMPRSS2 in influenza A virus replication, the precise determinants of influenza protease dependency remain unclear." (PMID 40882005, 2025). "Using the Human Cell Atlas consortium respiratory single-cell RNA-seq data (reflecting the transcriptome of uninfected cells), we compared the expression of proteases previously identified to activate influenza HA: TMPRSS2, TMPRSS4, matriptase/ST14, HAT/TMPRSS11D, and furin." (PMID 40882005, 2025). "In addition to its role in influenza, TMPRSS2 extends its influence to the activation of other respiratory viruses." (PMID 39858469, 2025). "Human TMPRSS2 is a type II trypsin-like transmembrane serine protease that has attracted substantial interest for apparent roles in facilitating host infection by various forms of influenza and coronaviruses." (PMID 37987478, 2023). "We then examined whether the non-flagellated, Gram-positive bacterium S. pneumoniae that is commonly identified as a co-infecting pathogen in influenza pneumonia is able to stimulate TMPRSS2 expression in Calu-3 cells." (PMID 37208193, 2023). "Therefore, drug development targeting TMPRSS2 also provides us with alternative solutions to treat influenza." (PMID 37990007, 2023). "Our TMPRSS2−/− pig model was created to address the role of TMPRSS2 in swine influenza pathogenesis but may also improve our knowledge of therapeutic approaches to human influenza disease." (PMID 38883409, 2023). "Bromhexine hydrochloride is shown to inhibit protease activity of TMPRSS2 in metastatic prostate cancer of mice, and accordingly, it could also be used for the treatment of both influenza and coronavirus infections." (PMID 34445373, 2021). "Notably, TMPRSS2 has also been shown to cleave the hemagglutinin protein of influenza viruses, a step necessary for influenza infectivity." (PMID 33310900, 2020). "TMPRSS2 is also involved in the entry of other respiratory viruses such as influenza, suggesting that modulating its expression may also be effective in deterring entry and spread of other viruses." (PMID 33164753, 2020). "The use of TMPRSS2 to successfully generate PVs expressing HA from various subtypes has been previously reported, and TMPRSS2 was used to generate the first reported equine influenza PV." (PMID 27983716, 2016). "It is therefore tempting to speculate that TMPRSS2 and HAT might also support viral spread outside the lung and might thus contribute to complications associated with influenza infection, like gastrointestinal manifestations, myocarditis and encephalopathy." (PMID 22558251, 2012). "It is worth noting that furin, which cleaves polybasic motifs in highly pathogenic influenza and in SARS-CoV-2, contains a more extensive extracellular region with predicted disorder, which may confer greater conformational flexibility to the serine protease domain as compared to TMPRSS2." (PMID 40882005, 2025). "In sum, these results demonstrate that cleavage-activation of influenza HA and SARS-S is conserved between human, porcine, avian and murine TMPRSS2 as well as human and murine HAT." (PMID 22558251, 2012). "Both TMPRSS2 and HAT are type II transmembrane serine proteases possessing trypsin-like activity and are known to be important for cleaving influenza HA required for productive infection." (PMID 22396727, 2012). "As a result, the critical involvement of TMPRSS2 in the infectivity and pathophysiology of viral respiratory infections such as SARS-CoV-2 and influenza makes it an attractive target for therapeutic interventions to reduce death and disability caused by these respiratory viruses." (PMID 40297833, 2025).
influenza (continued). "Elastase-dependent influenza is attenuated, as elastase is not present in high enough levels during infection to make up for the lack of TMPRSS2 or furin cleavage during virion formation." (PMID 38932275, 2024). "Consistent with other reports, we found that cells expressing TMPRSS2 supported influenza replication without the need for trypsin." (PMID 33413322, 2021). "TMPRSS2 has emerged as a useful drug target for antiviral drug discovery, and the lack of influenza and coronavirus infection has been confirmed in TMPRSS2 knock-out mice." (PMID 34222852, 2021). "Therapeutics targeting TMPRSS2 expression or activity may, therefore, be beneficial not only for coronavirus-infected patients but also those infected with influenza." (PMID 33310900, 2020). "Individual strains of influenza (low pathogenicity or high pathogenicity) may carry either a monobasic or polybasic cleavage site, which determines whether or not their HA can undergo furin cleavage or needs to be cleaved by another protease, such as HAT, TMPRSS2, and other trypsin-like proteases." (PMID 38932275, 2024). "Interestingly, TMPRSS2 was shown to activate mono- and multibasic HAs of H9N2 influenza strains, which are not activated by furin." (PMID 35163273, 2022). "Compromised transplacental transfer of anti–SARS-CoV-2 antibodies with robust transfer of influenza-specific immunity and nonoverlapping placental expression of SARS-CoV-2 receptors angiotensin-converting enzyme 2 and transmembrane serine protease 2 were noted." (PMID 33351086, 2020).
SARS-CoV infection (40 papers, 2012 to 2025). "For SARS-CoV entry, which is reported to be highly CatL-dependent, it has been shown that expression of the cellular transmembrane protease serine 2 (TMPRSS2) can overcome the block in SARS-CoV infection and replication caused by CatL inhibitors." (PMID 23236527, 2012). "We collected four GEO databases, GSE33267, GSE47962, GSE45042 and GSE156544, to assess TMPRSS2 expression during SARS-CoV infection." (PMID 35017320, 2022). "Although the TMPRSS2 gene is expressed in lower amounts than ACE2 and Ctsl, inhibitors of TMPRSS2 protein, such as ambroxol, can clinically reduce the severity of SARS-CoV infections." (PMID 35745615, 2022). "TMPRSS2, trypsin and catL are considered as potential targets to inhibit SARS-CoV infection dating back to 2003." (PMID 35746605, 2022). "The disease is caused by the SARS (Severe Acute Respiratory Syndrome)-CoV-2 coronavirus, which requires host cell proteins such as ACE2 (angiotensin-converting enzyme 2) and TMPRSS2 (transmembrane serine protease 2) for infection of lung epithelia." (PMID 34328182, 2021). "Later, a series of studies strengthened this prediction that TMPRSS2 plays a more significant role in comparison with the other proteases in SARS-CoV infection." (PMID 34336361, 2021). "GSE56677 and GSE52920 were both used to analyze the changes of TMPRSS2 expression in Vero E6 cells and mice lung after SARS-COV infection." (PMID 33193689, 2020). "Yet, successful SARS-CoV infection of TMPRSS2 knockout mice was observed, demonstrating the ability of SARS-CoV and suggesting the ability of SARS-CoV-2 to use Cathepsin B/L in vivo." (PMID 33290397, 2020). "Matsuyama and collaborators have shown that TMPRSS2 is expressed in lung tissues and is a fundamental determinant of viral tropism and pathogenicity at the initial site of SARS-CoV infection." (PMID 33143053, 2020). "We used GSE56677 and GSE52920 to study the in vivo and in vitro changes of TMPRSS2 after SARS-COV infection." (PMID 33193689, 2020). "The results showed that the expressions of TMPRSS2 in the control group was slightly decreased compared with the other group, and mice lungs after SARS-COV infection obviously increased compared with the control group." (PMID 33193689, 2020). "In Vero cells expressing TMPRSS2, the corresponding numbers were ~20% for E-64d, ~47% for camostat mesylate, and ~98% for both with SARS-CoV infection." (PMID 33290397, 2020). "For instance, with HeLa cells expressing ACE2, the effect of camostat mesylate was negligible in inhibiting SARS-CoV infection compared to its effect on the same cells engineered to overexpress TMPRSS2." (PMID 33290397, 2020). "Moreover, it has already been demonstrated in rats that the pharmacological inhibition of TMPRSS2 is effective against SARS-CoV infection." (PMID 38606293, 2024). "Briefly, the coronaviruses that cause severe acute respiratory syndrome (SARS), such as SARS-CoV, MERS-CoV (responsible for the middle east respiratory syndrome), and SARS-CoV-2, need transmembrane serine protease 2 (TMPRSS2) for their entry into the host cells." (PMID 38077924, 2023). "More importantly, TMPRSS2 expression was significantly decreased during SARS-CoV infection." (PMID 35017320, 2022). "In addition, GSE56677 and GSE52920 were used to study the expression changes of TMPRSS2 in vivo and in vitro after SARS-COV infection." (PMID 33193689, 2020). "Interestingly, a serine protease inhibitor camostat was known to inhibit transmembrane protease serine 2 (TMPRSS2) and effectively protected the mice against death caused by SARS-CoV infection." (PMID 32226290, 2020). "The consequence shows that TMPRSS2 expression levels in both of GSE56677 and GSE52920 were reduced after SARS-COV infection, suggesting that TMPRSS2 promoter methylation might be activated and display an increased level in PRAD." (PMID 33193689, 2020).